H3P21 (H3 histone pseudogene 21)
Synonyms: p01; H3.Z
Gene: Transcribed processed pseudogene on chromosome 5 (17,625,551 to 17,625,959, reverse strand). Ensembl gene ENSG00000250386.
Diseases named in the same sentence as H3P21 in open-access papers:
H3P21 is named in the same sentence as 4 diseases in open-access papers, as found by Europe PMC text mining. Sharing a sentence is not in itself a finding about the gene and the disease.
H3P21 shares sentences with these, for which no sentence is quoted: tumor (2 papers); cancer (1); glioblastoma (1); schwannoma (1).